IL20RA (interleukin 20 receptor subunit alpha)
Diseases named in the same sentence as IL20RA in open-access papers (continued):
Sharing a sentence is not in itself a finding about the gene and the disease.
metastatic cancer (1 paper, 2021). A carcinoma which has spread from the original site of growth to another anatomic site. "Immunohistochemical (IHC) analysis also shows the much lower level of IL20RA in metastatic cancer cells than that in the cancer cells at the primary sites." (PMID 34114949, 2021).
non-alcoholic steatohepatitis (1 paper, 2018). "The IL-20RA cytokine receptor has also been classified as being under miRNA control in non-alcoholic steatohepatitis." (PMID 29892294, 2018).
non-small cell lung carcinoma (1 paper, 2021). A group of at least three distinct histological types of lung cancer, including non-small cell squamous cell carcinoma, adenocarcinoma, and large cell carcinoma. "In contrast to our results, a previous study showed that the low expression of IL20RA was related to the poor prognosis in non-small cell lung cancer." (PMID 34820194, 2021). "Previous research found that IL20RA protein was upregulated in non-small cell lung cancer (Baird, Gray & O’Byrne, 2011), but no reports have been published about IL20RA protein expression in CRC." (PMID 34820194, 2021).
Obesity (1 paper, 2020). Accumulation of substantial excess body fat. "After further analyses of these shared gene-sets, overexpressed pro-inflammatory cytokines and cytokine receptors (e.g., IL11, IL20RA, IL27RA) could be linked to less thermogenic DN adipocytes, and thereby, to obesity and inflammation." (PMID 32316277, 2020).
osteoarthritis (1 paper, 2019). A noninflammatory degenerative joint disease occurring chiefly in older persons, characterized by degeneration of the articular cartilage, hypertrophy of bone at the margins and changes in the synovial membrane. "The expression of IL-20RA in RA-FLSs was higher than that in osteoarthritis-FLSs." (PMID 31831038, 2019).
spondylolisthesis (1 paper, 2026). A condition in which there is forward displacement of a vertebral bone over the on below it. "IP MR identified risk-increasing associations for LSS (4E-BP1 and interleukin-4), spondylolisthesis (CXCL1, CXCL5, FGF-5, IL-15RA, and IL-4) and IDD (IL-20RA and IL-6), while IL-18 showed a protective association with IDD that remained robust after multiple-testing correction." (PMID 42317351, 2026).
tuberculosis (1 paper, 2024). A chronic, recurrent infection caused by the bacterium Mycobacterium tuberculosis. "For example, the genes upregulated in Yakutian cattle in metacarpal adipose tissue and perirenal adipose tissue, such as TPRG1 and IL20RA, suggest adaptations related to feed efficiency and susceptibility to tuberculosis, respectively." (PMID 39333243, 2024).
tumor (19 papers, 2012 to 2025). "A recent study identified that IL-20RA is significantly expressed in colorectal cancer (CRC) tumor tissues and is associated with advanced stages of the disease." (PMID 40806452, 2025). "Higher expression of NR0B1 and IL20RA were associated with higher tumor histologic grade, and lower expression of ESRRG were associated with higher tumor histologic grade." (PMID 34868990, 2021). "Therefore, we proposed that the high protein expression of IL20RA was associated with oxygen binding and oxygen transporter activity, which might disturb the hypoxic microenvironment of tumor tissues in CRC." (PMID 34820194, 2021). "In NSCLC tumor samples and cell lines, IL-20RB and IL-22R1 are often overexpressed, while IL-20RA expression is suppressed, partly due to DNA CpG methylation and histone modifications." (PMID 40806452, 2025). "Overexpression of IL20RA was found in colorectal cancer (CRC) and was also associated with greater tumor diameter and poor prognosis." (PMID 39664380, 2024). "On the other hand, activation of IL20RA in ovarian cancer cells, when they disseminate into peritoneal cavity, results in polarization of macrophages into anti-tumor M1 subtype." (PMID 39664380, 2024). "IL-20RA affected the expression of PD-L1 by activating the Jak1-STAT3-SOX2 pathway in order to reduce the immunogenicity of tumor cells and exert the function of immune evasion." (PMID 34336707, 2021). "We first analyzed the expression of IL-20RA in the tumor tissue and adjacent normal colon tissue of 118 CRC cases." (PMID 34336707, 2021). "Most importantly, αPD-L1 Ab combined with NPs-Stattic-IL20RA significantly inhibited the tumor volume and tumor weight of 4T1-IL20RA allografts compared with IgG, αPD-L1 Ab, NPs-Stattic, and NP-Stattic-IL20RA plus IgG treatment groups, respectively." (PMID 33456560, 2021). "IHC staining revealed that αPD-L1 Ab in combination with NPs-Stattic-IL20RA inhibited the expression of p-STAT3 (Tyr705) and SOX2 in tumor tissues compared with IgG, αPD-L1 Ab, NPs-Stattic, and NP-Stattic-IL20RA plus IgG treatment, respectively." (PMID 33456560, 2021). "The results indicated that CRC patients with tumor size >4 cm had higher IL20RA expression than those with <4 cm (P = 0.023)." (PMID 34820194, 2021). "Analysis of the public microarray dataset GSE62598 revealed higher expression of Il20ra in 4T1 liver-aggressive explants compared with 4T1 primary tumor explants." (PMID 33456560, 2021). "Some literature also demonstrated the poor behaviors that IL20RA was correlated with were the important factors affecting patients’ tumor-related death (Vatandoust, Price & Karapetis, 2015)." (PMID 34820194, 2021). "We found that IL-20RA was highly expressed in the tumor tissue of CRC and related to the advanced stage." (PMID 34336707, 2021). "The mechanism by which IL20RA regulates the recruitment of immune cells to the tumor microenvironment still needs to be further investigated." (PMID 33456560, 2021). "In this study, the αIL20RA Ab was only used for targeting purposes to deliver stattic to the IL20RA+ tumor cells." (PMID 33456560, 2021). "We found that the expression of IL-20RA was significantly increased in tumor tissues compared with normal tissues." (PMID 34336707, 2021). "We found that IL20RA overexpression boosted the expression of the stemness marker genes Nanog and Sox2 in tumor tissues in vivo and increased the number of lung metastatic foci." (PMID 33456560, 2021). "We found that super-enhancer inhibition by JQ-1 or iBET-151 suppressed the growth of tumor cells and inhibited the expression of IL-20RA." (PMID 34336707, 2021). "While IL10RB is widely expressed on hematopoietic cells, IL20RA usually occurs only in activated immune cells; expression of both receptors on tumor cell lines and tissues has been described." (PMID 31948053, 2020).
tumor (continued). "The presence of IL10RB/IL20RA in tissue was associated with shorter survival time, compatible with the notion that IL26 signaling per se contributes to tumor progression." (PMID 31948053, 2020). "Wild-type-MDA-7/IL-24 monomers aggregate to form dimers, which then bind and activate defined molecular pathways downstream of IL-20Rα/β receptors to inhibit tumor cell proliferation and survival." (PMID 22808125, 2012). "The epigenetic silencing of IL-20RA has been correlated with poorer disease-free survival in NSCLC, suggesting that loss of IL-20 signaling may contribute to tumor progression." (PMID 40806452, 2025). "IL20 receptor subunit alpha (IL20RA) signaling, which explicitly enhances BC stemness and creates an immune milieu favorable to tumor growth, may be involved in forming numerous tumor formations." (PMID 37970212, 2023). "Furthermore, IL-20RA was highly expressed in the tumor tissue of colorectal cancer (CRC) and related to the advanced stage and poor patient prognosis." (PMID 36859240, 2023). "In addition, this combination treatment enhanced the expression of CD8α and CD11c in tumor tissues compared with IgG, NPs-Stattic, and NP-Stattic-IL20RA plus IgG treatment, respectively." (PMID 33456560, 2021). "In addition, expression of Sox2/SOX2 and Il20ra/IL20RA was enriched in the sorted SP and/or tumor spheres of EO771FL and T-47D cells." (PMID 33456560, 2021). "The results showed that IL-20RA was correlated with several classic tumor-related signaling pathways, such as KRAS, hypoxia, and EMT pathway, which might lead to promotion of tumor proliferation, migration and invasion." (PMID 34336707, 2021). "Furthermore, by multivariate Cox regression analysis, we revealed that the overall survival of CRC was related not only to the expression of IL20RA protein but also to the degree of tumor differentiation and TNM stage." (PMID 34820194, 2021). "To test this hypothesis, we constructed a novel IL20RA-targeted liposomal NP carrying the STAT3 inhibitor stattic (NP-Stattic-IL20RA) to target IL20RA+ tumor cells." (PMID 33456560, 2021). "Knockdown of IL20RA in CRC cell lines downregulates Janus kinase 1 (JAK1) and signal transducer and activator of transcription 3 (STAT3) and consistently suppress tumor growth." (PMID 39664380, 2024). "IL-20RA, driven and regulated by SEs, plays essential roles in CRC, not only in tumor progression but also prognosis." (PMID 34336707, 2021). "We also detected other epigenetically regulated genes in this signature, including CD70, IRAK, IL20RA, THBD, TACSTD2, and MST1R, with implications related to the tumor immune microenvironment." (PMID 34150764, 2021). "The effects of extracellular MDA-7/IL-24 are mediated by binding to IL-20Rα/β receptors on tumors cells, inducing modulation of the ERK, JNK, MAPK pathways to induce anti-tumor effects." (PMID 22808125, 2012). "To assess the anti-tumor activity of LV-SM7L, we transduced U87MG (high IL-20Rα/β) or H4 (low IL-20Rα/β) human GBM cells with LV-SM7L, LV-M7 or control." (PMID 22808125, 2012). "IL20RA and SOX2 were increased in tumor tissues compared to normal/para-carcinoma tissues." (PMID 33456560, 2021). "Compared with the control group, the IL20RA-targeted NPs group exhibited a ~2-fold higher accumulation of DOX in tumor tissues, while the nonspecific accumulation of DOX in the non-targeted organs such as liver, spleen, kidney, and intestine was reduced." (PMID 33456560, 2021). "In this study, we first found that IL20RA protein was upregulated in CRC compared with the level in adjacent normal tissues, which was not influenced by sex, age, or tumor site." (PMID 34820194, 2021). "Interestingly, we found their receptors, IL17RA/IL17RC for IL17A/IL17F, IL10RB/IL22RA1 for IL22, and IL20RA/IL10RB for IL26, were upregulated in tumor cell than in normal epithelial cells." (PMID 35999201, 2022).
cancer (15 papers, 2013 to 2025). A tumor composed of atypical neoplastic, often pleomorphic cells that invade other tissues. "Recent data have associated IL-20RA signalling with hallmarks of cancer, including regulation of proliferative signalling, resistance to cell death, and activation of cellular migration and invasion." (PMID 39941053, 2025). "In recent decades, increasing evidence has related the involvement of the IL-20 receptor subunit alpha (IL-20RA) axis with the development and progression of many disorders, including inflammatory diseases and cancer." (PMID 39941053, 2025). "Although studies on IL20RA have primarily concentrated on immune modulation and cancer-related aspects, investigations regarding oxidative stress are limited." (PMID 39765872, 2024). "Recently, IL20RA has been identified as one of the receptors of B7-H3,104,223 and its expression is found predominantly on epithelial cells and carcinomas, suggesting cancer cell-cancer cell B7-H3-IL20RA interaction in cis or in trans." (PMID 38773064, 2024). "The significance of IL20RA as a biomarker in cancer has been addressed, and overexpression of IL20RA alone promotes cancer stemness via the transcription factor SOX2 and induces an immunosuppressive TME by increasing PD-L1 expression." (PMID 36284349, 2022). "Recent studies have provided evidence that IL20RA signaling regulates the development of certain cancers." (PMID 34868990, 2021). "To further get the clinical evidences on the relevance of IL20RA in OC metastasis, we collected primary OC tissues and paired cancer cells isolated from ascites and metastatic nodules in peritoneal cavity from 20 serous OC patients." (PMID 34114949, 2021). "Most importantly, our study highlighted a prominent role of IL20RA in driving a cancer-favorable immune environment via reduction of CD8+ T-cell, and NK-cell infiltration." (PMID 33456560, 2021). "In contrast, the WNT5A+ inflammatory fibroblast interacts with cancer cells via IL24:IL20RA and WNT5A:FZD5 pathways, which could promote cancer progression and chemoresistance." (PMID 38744958, 2024). "Based on this finding, we hypothesized that IL20RA might promote the formation of an immune environment favorable to cancer cells." (PMID 33456560, 2021). "To further investigate the relevance of IL20RA with OC metastasis, we analyzed the correlation between the IL20RA level and the survival of serous OC patients given that metastasis accounts for over 90% of cancer death." (PMID 34114949, 2021). "Current studies provide evidences that IL20RA signaling regulates the development of cancer." (PMID 33456560, 2021). "Moreover, IL-20RA regulates several oncogenic and immune pathways contributing to invasion and metastasis in carcinoma progression." (PMID 34336707, 2021). "For example, IL-20RA and IL-22RA1 expression is confined to specific tissues and is essentially absent from hematopoietic lineages; thus, the selective distribution underscores the specialized roles of these cytokines in tissue homeostasis and in several diseases, including cancer." (PMID 40806452, 2025). "Analysis of IL20RA protein by western blot shows a dramatic decrease of IL20RA in the transcoelomic spread cancer samples when compared with those from the primary sites, which is confirmed by the quantitative reverse-transcriptase-PCR (qRT-PCR) analysis of IL20RA mRNA." (PMID 34114949, 2021). "Mechanistically, IL-20RA promoted such effects via the JAK1–STAT3–SOX2 signaling pathway, beyond promoting a cancer-favorable immune microenvironment through the increased PD-L1 expression." (PMID 40806452, 2025). "The results showed that knockdown of IL-20RA in LoVo cells significantly reduced the expression of Snail and Slug, which activate EMT markers in cancer cells." (PMID 34336707, 2021).
cancer (continued). "In addition, IL20RA activates the Janus kinase 1 (JAK1)-STAT3-SOX2 signaling pathway, leading to increased expression of PD-L1 and reduced recruitment of anti-cancer lymphocytes, including CD8+ T cells and natural killer cells." (PMID 33456560, 2021).
infection (4 papers, 2013 to 2025). The state of being infected such as from the introduction of a foreign agent such as serum, vaccine, antigenic substance or organism. "Our additional study also tested a 10-fold lower dose of viral inoculum (1 × 105 PFU/mouse) and obtained similar results as those of high viral dose (1 × 106 PFU/mouse), showing that IL-20RA deficiency ameliorates EV-A71 infection in mice." (PMID 41550952, 2025). "Overall, IL-20RA deficiency significantly promotes macrophage polarization toward the M1 phenotype in mice during infection." (PMID 41550952, 2025). "Because all three mouse IL-20RA cytokines were detected in WT mice, we next investigated their significance in EV-A71 infection by comparing WT and IL-20RA-/- mice." (PMID 41550952, 2025). "EV-A71 infection induced IL-12 in both WT and IL-20RA-/- mice, with reduced serum IL-12 levels detected in WT mice when compared to IL-20RA-/- mice from 1 to 5 d.p.i., with significant differences found on 3 and 5 d.p.i.." (PMID 41550952, 2025). "As all three mouse IL-20RA cytokines are constitutively expressed and IL-10 is induced after infection, this suggests that both IL-19 and IL-20 could be the upstream effectors to induce IL-10." (PMID 41550952, 2025). "As IL-20RA is detected on leukocytes such as macrophages, 51D treatment may deplete the protective leukocytes and result in the failure to reduce EV-A71 infection." (PMID 41550952, 2025). "Our in vivo results showed that IL-20RA deficiency reduces the level of T cells expressing IL-10 and M2 macrophages but increases the levels of macrophages expressing IL-12 and IFN-γ and M1 macrophages in mice during infection." (PMID 41550952, 2025). "EV-A71 infection increased the percentages of CD45+IL-12+ cells in both WT and IL-20RA-/- mice, with a reduced percentage detected in WT mice when compared to IL-20RA-/- mice." (PMID 41550952, 2025). "After infection, the percentage of CD45+IL-10+ cells in the splenocytes of WT mice was higher than that of IL-20RA-/- mice." (PMID 41550952, 2025). "Most of the genes for chemokines/chemokine receptors (CCR2, CCR6, CCR7, CSF2RB, CX3CR1 and CXCR4) and cytokines/cytokines receptors (IL1R2, IL8, IL18, IL20RA and IL22RA2) were down-regulated after infection by vvIBDV at 3 dpi." (PMID 33110122, 2020). "EV-A71 infection increased the percentages of CD45+IFN-γ+ cells in both WT and IL-20RA-/- mice, with a reduced percentage of the cells detected in WT mice when compared to IL-20RA-/- mice." (PMID 41550952, 2025). "In sera of WT mice, IL-20RA cytokines, but not IL-10, IL-12, or IFN-γ, were detected in mock-infected animals, and EV-A71 infection significantly increased IL-19 and slightly increased IL-20 levels." (PMID 41550952, 2025).
IL20RA also shares sentences with these, for which no sentence is quoted: asthma (2 papers); liver fibrosis (2); rheumatoid arthritis (2); airway hyperresponsiveness (1); atherosclerosis (1); bovine tuberculosis (1); cardiomyopathy (1); chronic asthma (1); chronic myeloid leukaemia (1); colitis (1); colorectal adenocarcinoma (1); Crohn disease (1); endometrial carcinoma (1); esophageal cancer (1); fibrosarcoma (1); fracture (1); gastric cancer (1); hematoma (1); inflammation (1); intestinal ulcers (1); lung carcinoid tumor (1); MALT lymphoma (1); myopathy (1); neurological diseases (1); pancreatic cancer (1); periodontitis (1); prostate adenocarcinoma (1); prostate carcinoma (1); pustular psoriasis (1); rectum adenocarcinoma (1).
A further 5 diseases each share a sentence with IL20RA in 1 paper.